CD36 (CD36 molecule (CD36 blood group))
Diseases named in the same sentence as CD36 in open-access papers (continued):
Sharing a sentence is not in itself a finding about the gene and the disease.
cancer (continued). "In addition, CD36 encodes important fatty acid transferases that not only are involved in fatty acid transport and lipid metabolism but also serve as potential prognostic biomarkers for cancer." (PMID 32511270, 2020). "Therefore, it is reasonable to speculate that the upregulation of CD36 associated with metabolic abnormalities may be linked to the cancer cell progression of GC." (PMID 31410220, 2019). "We hypothesize that upregulation of TFEB, PGC1α and PPARα as well as increasing lipid uptake via CD36 as discovered in our study is an escape mechanism, by which the cancer cells try to compensate for defective mitochondria and loss of energy induced by V-ATPase inhibition." (PMID 31358011, 2019). "Collectively, these findings underscore the novelty of CD36 as a metabolic-immune regulator in cancer and point toward future mechanistic studies to define its therapeutic potential." (PMID 41550652, 2025). "CD36 has also shown a positive relation with different immune regulators in all cancers, which provokes its immune regulatory role in immunotherapy." (PMID 41550652, 2025). "This study is based on bulk transcriptomics and genomic profiles and includes correlations that define CD36-mediated roles in various cancers that require in-vitro and in-vivo functional validation." (PMID 41550652, 2025). "We also evaluated CD36-related molecular pathways and immune signatures in cancer by a comprehensive GSEA analysis." (PMID 41550652, 2025). "Cancer cells can absorb fatty acids through fatty acid transporters (FATPs), fatty acid translocases (CD36), and fatty acid binding proteins (FABPs)." (PMID 40538442, 2025). "CD36 is a multifunctional scavenger receptor and fatty acid transporter that has shown a significant role in cancers through its involvement in lipid metabolism, immune modulation, and cellular adhesion." (PMID 41550652, 2025). "On the other hand, CD36 expression was correlated significantly with a higher cancer grade and stage (P=0.000 & 0.01, respectively)." (PMID 40060230, 2025). "The prognostic effect of CD36 has recently been investigated in many cancers and precancerous cells, and the results declared that the effect of CD36 on cancer relies on the type of cancer." (PMID 40060230, 2025). "Conclusively, this comprehensive multi-omics pan-cancer analysis reveals the heterogeneous and cancer-type-dependent role of CD36, integrating immune modulation, metabolic regulation, and therapeutic response." (PMID 41550652, 2025). "We advance the understanding of CD36's oncogenic role through a comprehensive multi-omics analysis of 33 cancer types, integrating clinical and molecular data with robust multiple-testing correction." (PMID 41550652, 2025). "When cancer cells are cocultured with adipocytes, they exhibit increased expression of cluster of differentiation 36 (CD36), leading to increased absorption of fatty acids (FAs) by the cancer cells." (PMID 39823981, 2025). "Concurrently, markers like HGF, EGF, MMP–1 and the scavenger receptor CD36 reflect processes of chronic inflammation, tissue remodeling, and metabolic reprogramming, which facilitate cancer cell proliferation and survival." (PMID 41194922, 2025). "Taken together, LA-m-mediated sensitization of cancer cells to ferroptosis was attributed to its ability to upregulate CD36 and ACSL4." (PMID 40077664, 2025). "In some cancers, CD36-driven lipid uptake promotes immune suppression and EMT, whereas in others it appears to limit unchecked proliferation and immune infiltration." (PMID 41550652, 2025). "Since CD36 promotes stemness in multiple cancer models, we analyzed the activity of D11 on HepG2 clonogenicity, using tumorsphere assays." (PMID 39967671, 2025). "Two key proteins involved in this process that are upregulated in cancer cells in close proximity to adipocytes are CD36 and fatty acid-binding protein 4 (FABP4)." (PMID 41228384, 2025).
cancer (continued). "The enhanced CD36 expression in metastatic tissues in omentum highlights the crucial interaction between CD36, adipocytes, and cancer cells, leading to metastasizing and worsening the prognosis." (PMID 40076482, 2025). "This study explores the impact of ionizing radiation on CD36 and PS expression in cancer cells and monocytes." (PMID 39752516, 2025). "Increasing evidence shows that upregulation of CD36 promotes cancer progression, invasiveness, and is negatively correlated with drug responses, patient prognosis and stemness in different oncotypes." (PMID 39833955, 2025). "Our methylation analysis revealed that CD36 methylation levels are significantly lower among different cancers, such as BLCA, COAD, READ, and UCEC." (PMID 41550652, 2025). "Cancers stimulate adipocyte lipolysis, releasing Fatty Acids [FAs] that cancer cells absorb via receptors like CD36 and FATP1, using them for membrane synthesis, energy, or signaling." (PMID 39757666, 2025). "In turn, the levels of fatty acid transporting proteins FATP2 and CD36 were similar or lower, respectively, in cancer tissues comparing to normal mammary gland tissues." (PMID 40759952, 2025). "Paired analysis also depicted a similar dysregulated pattern of CD36 expression across multiple-type cancers." (PMID 41550652, 2025). "Blocking CD36 palmitoylation or inhibiting its secretion is important for diminishing FA uptake by cancer cells." (PMID 39984452, 2025). "The FAs enter the cancer cell through specific FA receptors and binding proteins (e.g., CD36, FATP1) and are used for membrane synthesis, energy metabolism, or lipid-derived cell signaling molecules (derivatives of arachidonic and linolenic acid)." (PMID 40709184, 2025). "Subsequently, accelerated lipolysis leads to enhanced FA release and influx into cancer cells mediated by cluster of differentiation 36 (CD36)." (PMID 40076482, 2025). "GSEA also illustrated cancer-type dependent enrichment of CD36 in cancer pathways, particularly immune and inflammatory pathways, while showing an inverse relation with proliferative and cell cycle pathways." (PMID 41550652, 2025). "In contrast, in adults, CD36 expression was significantly higher in AML when compared to other types of cancer, and the increase or even the expression of CD36 is associated with several factors that appear to be associated with a poor prognosis." (PMID 40527069, 2025). "There are also studies suggesting that fatty acid uptake promotes the transcription and function of CD36 through activation of the NF-kB pathway, leading to cancer metastasis and the formation of a malignant cycle." (PMID 41421797, 2025). "Recent studies have focused on CD36 as a target for cancer as it is involved in fatty acid transport and metabolism during cancer metastasis." (PMID 40867868, 2025). "Kaplan-Meier (KM) survival analysis revealed that prognostic significance of CD36 expression is dependent on cancer type." (PMID 41550652, 2025). "These suggest that these five cholesterol-related genes (APOA1, APOC3, ABCA1, NPC2, CD36) play an important role in cancer." (PMID 40302802, 2025). "The aim of study is to investigate oncogenic ability of CD36 in various cancers as a significant prognostic factor and a noteworthy contribution to immunogenicity." (PMID 41550652, 2025). "Fatty acids are not only synthesized intracellularly by FASN but also taken up from the extracellular environment through CD36, a fatty acid translocase that has emerged as a therapeutic target in cancer." (PMID 40552664, 2025). "For example, CD36, a long‐chain free fatty acid transporter, has been found to be overexpressed in various cancers, such as oral SCC, prostate carcinoma, and colorectal carcinoma." (PMID 40956032, 2025). "Recently, using an in vitro EC model, it was demonstrated that heme metabolism reduces phagocytosis by modulating the secretion of TLR4-mediated IFN Iα as well as CD36 expression; contributing to events leading to immune escape in this cancer." (PMID 40871563, 2025).
cancer (continued). "We performed a comprehensive pan-cancer analysis of CD36 by using data from TCGA, integrating transcriptomic, proteomic, methylation, mutational, immune infiltration, immunotherapy, and drug sensitivity datasets." (PMID 41550652, 2025). "CD36 methylation analysis revealed lower methylation levels in several cancers, particularly in BLCA, LIHC, and UCEC." (PMID 41550652, 2025). "We adopted a comprehensive multi-omics pan-cancer approach to explore CD36's contribution to cancer biology and its clinical potential." (PMID 41550652, 2025). "Cancer cells expressing high levels of the receptor CD36 and lipid metabolism genes are more likely to initiate metastasis." (PMID 40814339, 2025). "Targeted inhibition of CD36 can suppress the growth and metastasis of multiple cancers, indicating its crucial role in cancer development." (PMID 40718481, 2025). "Cancer cells increase the uptake of exogenous lipids by upregulating the expression of FA transporters, such as CD36, and FABPs (FA-binding proteins)." (PMID 41306968, 2025). "In most cancer studies, CD36 primarily functions as a fatty acid (FA) transporter, mediating the uptake of extracellular FAs to support the metabolic needs of cancer cell proliferation and metastasis." (PMID 41267927, 2025). "We found that CD36 expression pattern is dysregulated in multiple cancer types, whereas higher expression correlated with poor prognosis in LGG, BRCA, CESC, and LAML." (PMID 41550652, 2025). "Cancer cells overexpressing FAs transporters, such as CD36, scavenge extracellular lipids extensively, resulting in cancer cell nutrient deprivation and leading to functional exhaustion of T cells." (PMID 41306968, 2025). "The role of CD36 in tumors has garnered significant attention; however, its function in cancer remains controversial." (PMID 41267927, 2025). "In tumors, CD36 is expressed not only by cancer cells but also by stromal cells and immune-infiltrating cells." (PMID 40723225, 2025). "Several genes altered during activation are approved or potential drug targets, including HMGCR, FADS1/2 and CPT1A, while others, such as FASN, CD36, and CTSD, are directly implicated in cancer-related processes." (PMID 40759959, 2025). "The possible mechanism by which CD36 affects recurrence is the cancellation of dormancy for cancer cells due to oxidative stress." (PMID 41465497, 2025). "Here we present a drug-like inhibitor providing a blueprint for further compound development and drug discovery targeting CD36, a central molecule in lipid metabolic reprogramming of cancer cells." (PMID 38643249, 2024). "Together with CD36, the family of FABPs has been investigated most frequently in the context of cancer." (PMID 39085485, 2024). "CD36 has also been shown to be expressed in multiple human cancer cell lines including those derived from pancreatic, ovarian, breast, and prostate cancer." (PMID 38218979, 2024). "CD36 is highly expressed in many types of cancers, including HCC, breast cancer, oral squamous cell carcinoma, acute myeloid leukemia and CRC." (PMID 39551780, 2024). "Increased CD36 expression is enriched in metastatic sites of many cancer types, including CRCM, and CD36 silencing, or CD36-blocking antibodies significantly reduce metastasis." (PMID 39125923, 2024). "A study shows that fatty-acid-mediated metabolic communication occurred through CD36 metabolic symbiosis between cancer cells and macrophages." (PMID 39062552, 2024). "High levels of either CD36 or CD47 are both prognostic indicators of poor outcomes for cancer patients." (PMID 38218979, 2024). "Free fatty acids can also be absorbed into cancer cells via overexpression of fatty acid translocase (CD36) or fatty acid transport proteins (FATPs)." (PMID 37939296, 2024). "In gemcitabine-treated patients, CD36 expression in resected pancreatic ductal adenocarcinoma (PDAC) specimens was also correlated to cancer prognosis." (PMID 38370376, 2024).
cancer (continued). "CD36 is a fatty acid transport protein, which has been shown to facilitate the uptake of fatty acids released from adipocytes into cancer cells." (PMID 39456610, 2024). "Cancer cells proliferate by fatty acids (FAs) uptake via utilizing plasma membrane FA protein transporters, such as CD36, the family of FA transport proteins (SLC27), and plasma membrane FA-binding proteins (FABPs)." (PMID 39273384, 2024). "CD36 is a scavenger receptor that performs various important functions in cancer such as regulating lipid uptake, immune recognition, inflammation, adhesion, and cell death in various cells." (PMID 38962317, 2024). "An acidic pH promotes CD36 expression, lipid uptake, and lipid droplet formation across cancer cells from varying tissues." (PMID 39188677, 2024). "In the TME, which is a complex ecological biosystem, multiple cell types, including CD36+ CAFs, plasma cells, and cancer stem cells (CSCs), interact with each other and influence ICIs prognosis." (PMID 38343549, 2024). "In recent years, it has been gradually proposed that CD36 plays a key role in multiple types of cancer." (PMID 38319449, 2024). "Cancer cells can absorb fatty acids through fatty acid transporter proteins (FATPs), fatty acid translocase (CD36), and fatty acid binding proteins (FABPs)." (PMID 39090116, 2024). "[123I]BMIPP is taken up by cancer cells via CD36 and FATP and incorporated into mitochondria via CPT1." (PMID 39062992, 2024). "The overexpression of CD36 in cancer cells has reportedly been to enhance the transcription of genes associated with metastasis formation, facilitating the spread of cancer to lymph nodes in mice." (PMID 39834807, 2024). "Cluster of differentiation 36 (CD36) plays an important role in cancer, inflammation, and metabolic diseases." (PMID 39524404, 2024). "In our review, we set out to explore the most prominent studies on the implication of CD36 in resistance to platinum-based drugs and other adjuvant cancer therapies in solid and haematological neoplasia." (PMID 38370376, 2024). "Conversely, palmitic acid or a high-fat diet increased the metastatic potential of CD36+ cancer cells." (PMID 38659591, 2024). "CD36 is a receptor of fatty acids that can promote the development of cardiovascular diseases and cancer." (PMID 38319449, 2024). "CD36 plays important role in cancer progression by promoting the stemness, growth and metastasis of cancer cells." (PMID 39551780, 2024). "CD36 is a widely reported molecule for its role in cancer progression and is overexpressed in many cancers." (PMID 39062552, 2024). "The coexistence of cancer cells with adipocytes leads to the elevation of CD36 expression, resulting in an enhanced absorption of fatty acids by cancer cells." (PMID 38933330, 2024). "Namely, cancers can upregulate CD36 to increase fatty acid (FA) uptake, increase FA synthesis, upregulate fatty acid oxidation (FAO) pathways, and increase the formation of lipid droplets to protect themselves from lipotoxic stress." (PMID 39188677, 2024). "In the following section, we present the most prominent studies of the past decade focusing on the modulation of CD36 in different cancer settings emphasizing drug resistance." (PMID 38370376, 2024). "Targeting the dysregulated lipid metabolism in cancer through the inhibition of transporters CD36 and FABP4, the disruption of de novo lipogenesis, and FAO enzymes, as well as cholesterol synthesis, has revealed potential avenues for therapeutics." (PMID 38610991, 2024). "CD36-mediated Ox-LDL uptake causes CD8+ T cell lipid peroxidation, which inhibits IFN-γ and TNF production via p38 kinase activation, favoring cancer cell proliferation." (PMID 39290325, 2024). "The potential targeting of CD36 in cancer therapy has been proposed due to these multifaceted roles." (PMID 39431237, 2024).
cancer (continued). "This supports work in mice as relevant to human cancers, and that metabolic programming of TAMs is CD36-dependent." (PMID 39742252, 2024). "Intriguingly, the oxidation of Cys272 and Cys333 promoted the activation of CD36, suggesting a regulatory effect of the redox signaling in the reactivation of dormant cancer cells." (PMID 38659591, 2024). "In terms of expression, CD36 was found to be highly expressed in control groups of various cancers, including BRCA and COAD, but was only highly expressed in KIRC and LIHC." (PMID 38742843, 2024). "The results showed that [123I]BMIPP accumulation was decreased in the presence of SSO and lipofermata in H441, LS180, and DLD-1 cells, suggesting that FATPs and CD36 are involved in [123I]BMIPP uptake in cancer cells." (PMID 39062992, 2024). "This analysis of the NCI GDC database supports our previous findings and indicates that the CD36/CD47 dual marker can be broadly used to select patients for VT1021 by cancer indication and progression." (PMID 39627379, 2024). "As the accumulation mechanism, [123I]BMIPP is mainly taken up by cancer cells via the fatty acid transporters CD36 and FATPs and incorporated into mitochondria via CPT1." (PMID 39062992, 2024). "CD36 is a critical participant in cancer development and progression via lipid uptake, immunological recognition, apoptosis, and anti-angiogenesis." (PMID 38370376, 2024). "Omental adipocytes have been shown to provide energy for proliferating EOC via the direct transfer of fatty acids to neighbouring cancer cells, while suppression of this process through inhibition of CD36 or FABP4 can sensitize EOC to chemotherapy." (PMID 39285292, 2024). "This review aims to highlight the impact of CD36 on cancer therapies with an emphasis on drug resistance and the direct targeting of CD36 for improving cancer control." (PMID 38370376, 2024). "CD36 has been shown to be expressed in multiple human cancer cell lines including those derived from pancreatic, ovarian, breast, and prostate cancer." (PMID 39627379, 2024). "CD36 mediates oxidized LDL uptake to promote MIF expression, which promotes immunosuppressive MDSC accumulation and accelerates cancer progression, and CD36 inhibitors enhance the treatment efficacy of immunotherapies." (PMID 38783357, 2024). "CD36 is an emerging target in cancer but most of CD36-targeting drug candidates that demonstrated efficacy in preclinical studies failed in humans because of severe adverse events and unsatisfactory efficacy." (PMID 39737196, 2024). "Studies have revealed that overexpression of CD36 is commonly observed in various tumors and can regulate lipid uptake, oxidation, and synthesis, thereby influencing the growth and migration of cancer cells." (PMID 38440405, 2024). "These FFAs are then taken up by cancer cells via CD36 and FABP3/4 to form LDs, which act as energy sources for malignant cells." (PMID 37700339, 2023). "Evidence for the suppression of CD36 and other components of the PPARγ transcriptional program was observed during the progression of multiple human cancers, including breast, colon, and lung cancers." (PMID 37816052, 2023). "Adipocytes are stimulated by cancer cells to release fatty acids into metastatic niche, and, in turn, adipocytes induce expression of fatty acid receptor CD36 on cancer cells, thus enhancing uptake of fatty acids by cancer." (PMID 37448521, 2023). "Here, we discuss the multifaceted role of CD36 in cancer biology, such as its role in mediating metastasis, drug resistance, and immune evasion to showcase its potential as a therapeutic target." (PMID 37371076, 2023). "As a scavenger receptor for LCFAs and oxidized LDL, CD36 is highlighted in recent studies as an emerging target for cancer therapeutics." (PMID 37063269, 2023). "In mice model, inhibition of CD36 has been shown to attenuate the metastasis of several cancers, including HNSCC." (PMID 37927468, 2023).